FGF23 (fibroblast growth factor 23)
Diseases named in the same sentence as FGF23 in open-access papers (continued):
Sharing a sentence is not in itself a finding about the gene and the disease.
tumor (continued). "The findingsof profound renal phosphate wasting initiated further evaluation, which revealedan elevated fibroblast growth factor 23 level and a right proximal fibularmesenchymal tumor on octreotide scintigraphy." (PMID 31850815, 2019). "In these tumors, spindle-shaped tumor cells, which are considered the principal source of FGF23 in TIO, were positive for Klotho staining." (PMID 30627598, 2019). "Systemic venous sampling that detects the excess production of FGF23 in the culprit tumor has recently emerged as greater technique for precise definition of tumor location." (PMID 28193220, 2017). "FGF23 exerts autocrine effects on the proliferation of tumor cells as several solid tumor cells express FGF receptors." (PMID 28300755, 2017). "The presence of osteochondral tissue in the intraosseous tumor is most likely due to the overproduction of FGF23 that triggers the differentiation of mesenchymal cells into chondrocyte and osteocyte, and promotes the proliferation of chondrocytes." (PMID 28193220, 2017). "When testing antigen expression, FGF23 is positive in about 70 % of all the cases studied, and the proliferating cells within the tumour are usually the source of FGF23." (PMID 26744291, 2016). "Third, result of quantitative ELISA-like immunohistochemistry was affected both by FGF23 expression level of each tumor cell and by density of the tumor cells." (PMID 27034530, 2016). "By contrast, tumours secrete FGF23 to concentrations that are several hundred-fold higher than normal levels, leading to dysregulation of FGF23 degradation pathway." (PMID 26744291, 2016). "After the FGF23-producing tumor is located and fully resected, long-term follow-up is advocated for early diagnosis of a potential recurrence." (PMID 27709474, 2016). "Tumour removal is always curative, and following complete resection of the tumour, the recovery and improvement of the patients is relatively quick, FGF23 disappears rapidly from the circulation, and serum phosphate returns to normal by day 5 post operation." (PMID 26744291, 2016). "Serum FGF23 concentrations are significantly elevated in TIO patients while decreasing dramatically after complete tumor removal (the reported plasma half-life was 46–58 min)." (PMID 27034530, 2016). "Regardless of tumour morphology, the hallmark of the diagnosis is the association of the tumour with the clinical syndrome of TIO, which includes an elevation in plasma FGF23 and its disappearance after tumour resection." (PMID 26744291, 2016). "Long-term follow-up is recommended, FGF23 can be used as a tumor marker for early detection of recurrences." (PMID 27709474, 2016). "Complete surgical resection of the FGF23 secreting tumor is the only definitive therapy, which emphasizes the need for localizing FGF23-producing tumors." (PMID 27709474, 2016). "Excision of the tumor resulted in normalization of serum phosphate and fibroblast growth factor 23 levels and in complete resolution of the clinical picture with disappearance of all musculoskeletal symptoms." (PMID 27709474, 2016). "It is known that FDG-PET/CT and measurement of FGF23 levels in limb with selective venous sampling are useful to estimate the tumor localization and that, if possible, the resection of tumor is the best therapy for the disease." (PMID 27867811, 2016). "On the other hand, it is often difficult to identify the localization of tumor, since most of the FGF23-producing tumors are benign and small, and these tumors have potential to occur anywhere in the body." (PMID 27867811, 2016). "Cultured tumor tissue produced high levels of intact FGF23 and demonstrated increased expression of HIF-1α protein." (PMID 27468359, 2016). "We should be aware of the possibility that phosphorus replacement therapy exert marked beneficial effects for the reduction of bone pain in subjects with FGF23-related hypophosphatemic osteomalacia even when we fail to identify tumor localization." (PMID 27867811, 2016).
tumor (continued). "The pan-selective FGFR inhibitor NVP-BGJ398 dose-dependently blocked the response to 10ng/ml FGF23, from which we chose 25 or 40nM (14 or 22ng/ml) to test against growth of MM cells stably secreting Gaussia luciferase to follow tumor burden." (PMID 25944690, 2015). "We tested if MM cells increased bone production of FGF23, using a novel ex vivo assay where tumor cells are added to primary bone organ cultures." (PMID 25944690, 2015). "VEGFA, PKIB and TMPRSS2 were increased by FGF23 stimulation in LNCaP cells while the tumor suppressor TXNIP was decreased." (PMID 26019137, 2015). "Additional work is needed to determine if NVP-BGJ398 acts primarily through direct blockade of FGF23 signaling or indirectly through other actions on tumor, bone, or both." (PMID 25944690, 2015). "It is possible that the tumor had been transformed from an FGF-23-producing tumor to a G-CSF-producing tumor." (PMID 24959220, 2014). "FGF-23 levels were significantly increased, and total body magnetic resonance imaging (MRI) revealed a tumor mass located at the distal tibia leading to the diagnosis of tumor-induced osteomalacia (TIO)." (PMID 25221676, 2014). "We experienced a rare case of acute prosthesis migration after hemihip arthroplasty due to FGF23-induced tumor." (PMID 23251177, 2012). "It is especially helpful in distinguishing which site is the FGF-23-secreting tumor when multiple sites are identified on imaging studies." (PMID 21611969, 2011). "In the present case, we had difficulty in localizing the FGF23-producing tumor." (PMID 39866919, 2025). "Notably, immunofluorescence analysis of the tumour stroma revealed immunopositive FGF23+ thin outgrowths extending in various directions and over different distances." (PMID 40981193, 2025). "According to Taijun Hana's research, intraoperative measurement of FGF23 levels may help determine whether the tumor has been fully excised, given that FGF23 has a short half-life of approximately 18.5 min." (PMID 39866529, 2025). "Based on these findings, we hypothesize that upon tumor cell metastasis to the liver, the secretion of fibroblast growth factors such as FGF23 and FGF3 may stimulate the phenotypic transformation of CAF precursor cells into VCAN_eCAF." (PMID 41258075, 2025). "Additional chemokines and growth factors, such as TGF‐α, CCL4, CCL20, IL‐17A, IL‐2RB, and FGF‐23, further underscore the multifaceted interplay between inflammation and tumor biology through pathways ranging from proliferation and angiogenesis to immune cell recruitment." (PMID 41458898, 2025). "The present study demonstrated that a number of spindle-shaped cells are FGF23+ and may serve as the structural and functional basis of tumour formation." (PMID 40981193, 2025). "In particular, bioinformatics analysis of MC interaction with other cells of the FGF23-producing tumour microenvironment, within an integral range of intertarget distances from 0 to 20 μm, disclosed their most frequent co-localisation with CD14+, CD31+, αSMA+, and CD163+ cells." (PMID 40981193, 2025). "Conversely, eliminating FGF23 expression in living organisms leads to a decrease in tumor growth." (PMID 39267764, 2024). "Furthermore, in a previous study conducted by our team, FGF23 was identified as a gene specifically expressed in UPSb tumours." (PMID 38397231, 2024). "Biochemical and radiographic findings suggested that an FGF-23-secreting tumour was present." (PMID 39506984, 2024). "A PET-CT scan labeled with 68-Ga-dotatate indicateda mesenchymal FGF-23-producing tumor." (PMID 38913332, 2024). "In addition to imaging, 61 patients (9.8%) had selective venous sampling for FGF23 to localize their tumor." (PMID 38913723, 2024). "Alongside its function as a marker in TIO, FGF23 has also been hypothesized to play a role in other neoplasms." (PMID 38806758, 2024).
tumor (continued). "For those who cannot undergo surgery or have incomplete tumor resection, replacement therapy with phosphates and active vitamin D may be an option, while FGF-23 monoclonal antibodies may be a potential targeted therapeutic agent." (PMID 37768354, 2023). "FGF23 can also be used in the follow-up after resection of the tumor." (PMID 35665817, 2023). "In patients over 20 years of age with a diagnosis of hyperphosphaturic hypophosphatemic OM and elevated FGF23 levels, without clinical manifestations suspicious of genetic origin, TIO should be suspected, and imaging tests be ordered to locate the possible FGF23-secreting tumor." (PMID 37048797, 2023). "In other tumor entities, increased FGF23 level is enigmatic." (PMID 36926025, 2023). "For some specific cases of TIO, venous FGF23 sampling can be used for localization of the tumor." (PMID 35665817, 2023). "Serum fibroblast growth factor 23 was related to tumor size (r = 0.344, P < 0.001)." (PMID 35857061, 2022). "Blood examination revealed a low serum phosphorus level of 2.3 mg/dL (reference range: 3.0-4.7 mg/dL), and a markedly high serum FGF23 level of 329 pg/mL (reference range: <50 pg/mL), and so we suspected PMT with TIO caused by the tumor-like lesion in the left fibula." (PMID 36686800, 2022). "The pathogenic mechanism of TIO is the excessive secretion of fibroblast growth factor 23 (FGF-23), a phosphatonin secreted by the tumor arising from mesenchymal tissue, which can result in reduced renal phosphate reabsorption and impaired vitamin D 1α-hydroxylase activity." (PMID 35016725, 2022). "In addition, although the expression of FGF23 in the tumor specimen has been confirmed by immunohistochemistry, it has not been confirmed by another method including chromogenic in situ hybridization (CISH)." (PMID 36686800, 2022). "This is in line with previous literature and might suggest that in an untreated patient, an increase in FGF23 level over time could represent an increase in tumor size." (PMID 35857061, 2022). "The tumor tissue concentration of FGF23 was significantly increased in 100 IU+cal 4T1 tissue; in 67NR tumors, it was increased in the 5000 IU and 100 IU groups as compared to the control 1000 IU group; and it was diminished in the 100 IU+cal as compared to the 100 IU group." (PMID 36230508, 2022). "Serum FGF23 and phosphate levels were shown to normalize after tumor removal within 1 h and 5 days, respectively, but complete bone healing may take up to 12 months." (PMID 35352187, 2022). "Interestingly, tumor size was significantly smaller in patients who had FGF23 measurements (median tumor size 2.5 cm) than in patients without reported FGF23 measurements (median tumor size 2.9 cm; P = 0.013)." (PMID 35857061, 2022). "Although his tumor could have expressed higher amounts of FGF23 mRNA during this period, this case also brings into question the reproducibility of FGF23 level and sensitivity of commercially available serum assays." (PMID 33615107, 2021). "Biopsy showed a phosphaturic mesenchymal tumor and chromogenic in situ hybridization (Mayo Clinic, Rochester, MN, USA) was positive for FGF23 mRNA, confirming this site as a likely TIO locus." (PMID 33615107, 2021). "TIO is mediated through inappropriate tumor overproduction of fibroblast growth factor 23 (FGF23)." (PMID 33191899, 2021). "Because the serum phosphate level in case 2 elevated gradually and remained lower, we performed 111In-pentetreotide scintigraphy, 18F-FDG PET/CT and systemic venous sampling of FGF23, which did not identify any causative tumor." (PMID 34901334, 2021). "After surgical resection of the tumor, serum C‐terminal FGF23 declined to <50 RU/mL 1‐week postoperative and was 90 RU/mL 3 weeks later (Mayo <180 RU/mL)." (PMID 33615107, 2021). "In OO, fibroblast growth factor 23 (FGF23) is overexpressed by the tumor." (PMID 34271987, 2021).
tumor (continued). "Also, the percentage of Vegf-a-expressing osteocytes correlates with MM tumor vascularity in vivo, and Fgf23, which is made by Ocys, increases Vegf-a production via autocrine signaling and Egr1 activity." (PMID 33057033, 2020). "In many other tumor entities, the biological role of an elevation of the plasma FGF23 concentration is still enigmatic, but FGF23 may serve as a (tumor) biomarker." (PMID 33520985, 2020). "While XLH has not previously been associated with the development of neoplastic disease, it has been observed that a higher plasma FGF23 concentration is associated with an increased risk of metachronous colorectal neoplasia." (PMID 29460029, 2018). "After successful tumor resection, the serum level of FGF23 decreases to a normal level within a few hours to days depending on the magnitude of the initial elevation (half-life of FGF23 is approximately 46–58 min)." (PMID 27709474, 2016). "Despite unraveling the pathophysiology of TIO, there is still often delay in establishing the diagnosis because associated musculoskeletal symptoms are non-specific, the FGF23-producing tumor is often very small and its localization very elusive." (PMID 27709474, 2016). "Our data suggested that the feasibility of immunohistochemical detection of FGF23 may depend on the level of secreted FGF23 from tumor cells." (PMID 26956379, 2016). "The immunohistochemical expression of FGF23 in PMTs may depend on the level of secreted FGF23 from tumor cells." (PMID 26956379, 2016). "Mesenchymal tumour itself may be related to fibroblast growth factor 23 (FGF23), which is responsible for hypophosphataemia and phosphaturia occurring in this paraneoplastic syndrome." (PMID 26744291, 2016). "Finally, FGF23 is produced and secreted by osteocytes and thus can act as a paracrine factor for nearby tumor cells so that FGF23 is likely to be a significant source of FGF signaling in the bone microenvironment." (PMID 26019137, 2015). "FGF23 knockdown resulted in significant decreases in tumor growth." (PMID 26019137, 2015). "Immunological studies revealed FGF-23-positive tumor cells and a Ki-67 index of 20%." (PMID 24959220, 2014). "In rare cases, a venous sampling of FGF-23 is necessary to detect the tumor." (PMID 25221676, 2014). "However, given that FGF-23 serum levels normalized after resection it is clear that the tumor must have produced FGF-23." (PMID 25221676, 2014). "The patient took various examinations, and FGF23-induced tumor was found in his right wrist." (PMID 23251177, 2012). "In some studies, FGF23 levels were determined by immunoassay before and after tumor resection." (PMID 23251177, 2012). "However, the tumor was resected, the renal function and serum FGF23 levels usually return to normal within 24 h." (PMID 23251177, 2012). "A diagnostic FGF-23 ratio was absent in 1 of 14 subjects whose tumor was a single highly suspicious lesion on imaging studies (false negative)." (PMID 21611969, 2011). "Recently, it has been demonstrated that some OOM-associated tumours, including PMTMCT, over express fibroblast growth factor FGF-23, a protein, which inhibits renal phosphate reabsorption by a mechanism distinct from that of other known phosphate homeostasis hormones." (PMID 21410940, 2011). "Additionally, selective venous sampling to measure FGF23 concentrations, combined with MRI, may aid in tumor localization." (PMID 39866529, 2025). "In addition, immunohistochemical histotopographic analysis revealed uneven distribution patterns of FGF23-producing cells of varying morphologies within tumour tissue, forming high-density loci that appear to constitute the structural basis for intratumoural contact and interaction." (PMID 40981193, 2025).
tumor (continued). "This study, to our knowledge, is the first to characterise features of the tumour microenvironment through spatial phenotyping of the immune and stromal landscape, together with histotopographic mapping of intercellular MC interactions with other subcellular populations in FGF23+ PMT." (PMID 40981193, 2025). "In addition to bone cells, FGF23 can also be produced by tumour cells." (PMID 38397231, 2024). "Although the first histopathological results by additional FGF23-mutation analysis of the tumor-DNA showed no relevant mutation, further investigations need to be conducted, since FGF23-mutation is only 1 of several possibilities for an overexpression of FGF23." (PMID 35204480, 2022). "FGF23 monitoring can also be used to detect tumor recurrence, which may require a second excision." (PMID 35352187, 2022). "Among them, spindle cells express FGF-23 and may be considered tumor parenchymal cells." (PMID 36615052, 2022). "The tumor may secrete other phosphatonins in addition to FGF23." (PMID 33818653, 2021). "Thus, FGF23 production and local inflammation may be interdependent in the microenvironment of the tumor depending on hypoxia, HIF-1α activation, and tumor-associated macrophages." (PMID 33520985, 2020). "This bone-like microenvironment could augment FGF23 production in tumor cells." (PMID 30627598, 2019). "Localization of FGF23-producing tumors can be challenging and a step-wise approach, including functional imaging, followed by anatomical imaging, and if necessary selective venous sampling may significantly improve success in tumor localization." (PMID 27709474, 2016). "Besides the increased serum FGF23 level, high FGF23 mRNA transcription and protein expression could also be detected in tumor specimens." (PMID 27034530, 2016). "Following tumor resection, FGF-23 levels may quickly decrease." (PMID 24137267, 2013). "Bone-derived growth factors such as insulin-like growth factor I/II (IGF-I/II), fibroblast growth factor 23 (FGF-23), and platelet-derived growth factor (PDGF) further enhance tumor colonization." (PMID 42291433, 2026). "FGF23 engages with αKlotho, a transmembrane protein that strengthens the attraction between FGF23 and its receptor FGFR, consequently exerting a profound influence on tumor cell signaling pathways, biological behaviors, and clinically pertinent indicators." (PMID 39267764, 2024). "Between baseline and cycle 3 day 1, the patient had a 4.8-fold increase in plasma FGF-23 (a marker of FGFR inhibition) levels, which was accompanied by 30% reduction in target tumor size." (PMID 38297981, 2024). "Recently, burosumab, a fully human monoclonal antibody which binds to and inhibits the activity of FGF23, has been approved in several countries for the treatment of TIO in cases where the tumor cannot be localized or curatively resected." (PMID 38913723, 2024). "In most cases of TIO, the elevated levels of fibroblast growth factor 23 (FGF-23) and/or Frizzle-4 protein produced by the tumor are responsible for the symptoms." (PMID 37768354, 2023). "Following tumor resection, TIO symptoms can be relieved, and blood FGF-23 levels can be restored to normal." (PMID 37768354, 2023). "Prior treatment of tumor organ cultures with HIF-1α inhibitors decreased HIF-1α and FGF23 protein accumulation and inhibited HIF-1α-induced luciferase reporter activity in transfected cells." (PMID 27468359, 2016). "In MM:bone cocultures, it decreased tumor RANKL, increased osteoblastic activity (type 1 collagen) and decreased osteocyte FGF23 - which in turn should decrease tumor heparanase." (PMID 25944690, 2015). "In patients who have elevated FGF-23 but no identifiable tumor, these patients typically take high-dose oral phosphate and activated vitamin D analogs to maintain serum phosphate." (PMID 41583152, 2025). "Based on these findings and labs, the nephrology and endocrinology team diagnosed an FGF-23-mediated disorder without an identified tumor." (PMID 41583152, 2025).